TLE1 (TLE family member 1, transcriptional corepressor)
Diseases named in the same sentence as TLE1 in open-access papers (continued):
Sharing a sentence is not in itself a finding about the gene and the disease.
lung carcinoma (continued). "Here, we examined whether TLE1 may protect lung cancer cells from anoikis induced by Bit1." (PMID 25003198, 2014). "Direct transcriptional suppression of E-cadherin expression by TLE1 via the transcription factor ZEB1 conferred enhanced anoikis insensitivity, anchorage-independent growth in vitro, and tumorigenicity in vivo of lung cancer cells." (PMID 29069783, 2017). "We have previously uncovered a novel role of the corepressor TLE1 in promoting cell migration and EMT in lung cancer through transcriptional repression of the epithelial marker E-cadherin." (PMID 29069783, 2017). "Given that ZEB1 has been shown to be the key transcription factor in repressing E-cadherin expression in lung cancer cells, we then examined if ZEB1 functions as the DNA-binding transcription factor mediating the observed TLE1-mediated E-cadherin repression." (PMID 29069783, 2017). "Notably, research has discovered that TLE1 has the ability to facilitate the suppression of the E-cadherin gene, which is a crucial controller of EMT in lung cancer cells." (PMID 37965333, 2023). "In addition, overexpression of TLE1 suppressed the expression of E-cadherin, induced epithelial-mesenchymal transition (EMT) in human lung cancer cells, and promoted the growth and metastasis of transplanted tumors in mice." (PMID 36438567, 2022). "Underscoring its role in anoikis insensitivity of lung cancer cells, the TLE1-mediated E-cadherin repression was negatively regulated by the tumor suppressor Bcl-2 inhibitor of transcription 1 (Bit1) to effect anoikis." (PMID 29069783, 2017). "Although TLE1 is not expressed in normal gastric mucosa, it has been detected in approximately 50% of gastric cancer patients, which is consistent with published data for breast and lung cancer." (PMID 27852056, 2017).
lung adenocarcinoma (10 papers, 2009 to 2026). A carcinoma that arises from the lung and is characterized by the presence of malignant glandular epithelial cells. "High TLE1 expression in lung adenocarcinoma is associated with a poor prognosis but, surprisingly, is associated with tumor inhibition and a better prognosis in pancreatic cancer." (PMID 36438567, 2022). "Although the survival signaling ErbB1 and ErbB2 signaling pathways have been shown to be activated in Grg1-induced lung adenocarcinomas, the molecular mechanism underlying the TLE1-induced lung oncogenicity remains to be fully elucidated." (PMID 29069783, 2017). "High levels of TLE1 in lung adenocarcinomas are associated with a poor prognosis, suggesting that TLE1 may be a lung tissue-specific oncogene." (PMID 36438567, 2022). "TLE1 was found to be overexpressed in approximately 11% of patients with lung squamous cell carcinomas and 20% of patients with lung adenocarcinomas." (PMID 27852056, 2017). "Here, using the human lung adenocarcinoma A549 and immortalized bronchial epithelial BEAS-2B cellular models, we present data in support of TLE1 as an effector of anoikis resistance, which is a determinant of malignant transformation and tumor progression." (PMID 29069783, 2017). "Transgenic mice overexpressing Grg1, a mouse homolog of TLE1, exhibited lung tumors which resemble human lung adenocarcinomas." (PMID 29069783, 2017). "Using the human lung adenocarcinoma A549 and immortalized bronchial epithelial BEAS-2B cell lines, we observed that TLE1 inhibits anoikis through transcriptional repression of E-cadherin gene." (PMID 29069783, 2017).
breast carcinoma (8 papers, 2013 to 2022). "In particular, TLE1 is a transcriptional repressor protein whose overexpression promotes resistance to anoikis (apoptosis after loss of cell attachment to the extracellular matrix) in human breast carcinoma cells." (PMID 23497166, 2013). "TLE1 promotes estrogen receptor (ER) target gene expression in breast cancer, leading to increased tumor cell proliferation." (PMID 36438567, 2022). "Recently, the critical role of TLE1 has been established in the progression of various tumors as; synovial sarcoma, gastric carcinoma, hematological malignancies and breast cancer." (PMID 34048198, 2021). "In breast cancer cells, TLE1 confers a survival advantage, at least in part, by blocking the Bit1-mediated apoptosis and anoikis pathway." (PMID 29069783, 2017). "In breast cancer cells, TLE1 binds the chromatin at ERα-binding sites and is required for optimal ERα recruitment." (PMID 25223786, 2014). "Furthermore, a strong association between TLE1 and the estrogen receptor has been discovered in breast cancer cells, where TLE1 assists the estrogen receptor in its interaction with chromatin and its proliferation-promoting function." (PMID 28296634, 2017). "EMT and anoikis resistance are known to promote the migration and survival of cancer cells that lose their cell–extracellular matrix (ECM) interactions, and these data suggest that TLE1 overexpression may promote lung and breast cancer metastasis by enhancing cancer cell migration and survival." (PMID 36438567, 2022). "Collectively, the data suggest TLE1 may be a novel target for breast cancer therapeutics." (PMID 27852056, 2017).
glioblastoma (7 papers, 2017 to 2024). The most malignant astrocytic tumor (WHO grade IV). "TLE1 and TLE3 are both implicated in cancer; TLE1, for example, promotes glioblastoma propagation and TLE3 stimulates cell division by suppressing myogenic differentiation via transcriptional repression of the master regulator MyoD." (PMID 37260146, 2023).
gastric cancer (6 papers, 2017 to 2022). A primary or metastatic malignant neoplasm involving the stomach. "Furthermore, TLE1 expression was associated with better prognosis in gastric cancer and human epidermal growth-factor receptor 2 (HER2)-positive or triple-negative breast cancer, and the clinical significance of the expression profile of TLE1 in several carcinomas was recently reported." (PMID 30053869, 2018). "Studies have shown that lnc-GIHCG overexpression increases the proliferation and migration of gastric cancer cells by upregulating TLE1 expression through the adsorption of miR-1281." (PMID 35528617, 2022). "Recent studies have demonstrated a critical role for TLE1 in the progression of various tumors, such as synovial sarcoma, hematological malignancies, gastric cancer, and breast cancer." (PMID 32432037, 2020). "Therefore, we consider TLE1 a tumor suppressor gene in PDAC, similar to liver and gastric cancer, which are both digestive system neoplasms, and TLE1 is a prognostic indicator for better outcomes." (PMID 32432037, 2020).
diabetes (5 papers, 2019 to 2026). "Considering that diabetes is a potent risk factor for most geriatric syndromes, the dysregulation of TLE1 in older passages can reflect the aging process." (PMID 36620623, 2022). "Associated cardiovascular diseases include diabetes (PDLIM5, HDAC4, and TLE1), cardiac development (PDLIM5) and myocardial aging (CASP12), hypertension (PFKP and TAB2), and intracerebral and intraventricular bleeding (RUNX1) and stroke (AXIN2)." (PMID 36620623, 2022). "In total, of the top five association signals that were mapped to genes (n = 103) we found five (CDKAL1, DCDC2C, KLF12, LPIN2, TLE1) to be related with diabetes." (PMID 31818369, 2019). "As some of the PDAC patients also had diabetes, TLE1 overexpression in the pancreatic ductal epithelium may have an antitumor role." (PMID 32432037, 2020).
malignant peripheral nerve sheath tumor (5 papers, 2019 to 2025). Malignant peripheral nerve sheath tumor (MPNST) is a rare and often aggressive soft tissue sarcoma occurring in a wide range of anatomical sites. "TLE1 expresses in other soft tumors as well; a recent study showed TLE1 expression in 82% of schwannomas, 39% in rhabdomyosarcoma, and 30% of malignant peripheral nerve sheath tumors." (PMID 31893185, 2019). "In their study, only a small subset of malignant peripheral nerve sheath tumor (MPNST) and solitary fibrous tumor (SFT) showed limited staining for TLE1." (PMID 31893185, 2019).
colon carcinoma (4 papers, 2009 to 2022). "In colon cancer, HDAC3 knockdown can suppress β-catenin translocation from the plasma membrane to the nucleus and increase the expression of Wnt inhibitors TLE1, TLE4 and SMO." (PMID 34991620, 2022). "Intriguingly, TLE1 alone could not suppress Notch signaling in colon cancer cells, but it could potentiate the suppressive activity of TLE5 by forming distinct nuclear foci containing TLE1, TLE5, and HDAC3." (PMID 36438567, 2022).
Ewing sarcoma (4 papers, 2020 to 2025). A small round cell tumor that lacks morphologic, immunohistochemical, and electron microscopic evidence of neuroectodermal differentiation. "A particular study compared TLE1 and NKX2.2 expression only in synovial and Ewing sarcomas." (PMID 32322158, 2020).
melanoma (4 papers, 2020 to 2025). A malignant, usually aggressive tumor composed of atypical, neoplastic melanocytes. "myogenic differentiation 1 (MYOD1), desmin, wilms tumor 1 (WT1), CD57,transducin-like enhancer of split 1 (TLE1), melanoma/prostate markers, chromogranin A, andinhibin were negative." (PMID 34106022, 2021). "Immunohistochemically, the tumor cells were positive for S100 (5/6), cyclin D1 (2/3), SATB2 (2/3), BCOR (2/4), and TLE1 (1/3) while negative for MUC4 (0/6), keratin (0/5), EMA (0/4), desmin (0/6), CD34 (0/6), SMA (0/5), SOX10 (0/5), and pan melanoma (0/2)." (PMID 40705064, 2025). "Immunohistochemically, the tumor cells were positive for S100 (5/6), cyclin D1 (2/3), SATB2 (2/3), BCOR (2/4), and TLE1 (1/3) while negative for MUC4 (0/6), keratin (0/5), EMA (0/4), desmin (0/6), CD34 (0/6), SMA (0/5), SOX10 (0/5), and melanoma cocktail (0/2)." (PMID 40705064, 2025).
schwannoma (4 papers, 2019 to 2025). A benign, usually encapsulated slow growing tumor composed of Schwann cells. "3+ TLE1 positivity was seen in one (100%) case each of infantile fibrosarcoma and low-grade fibromyxoid sarcoma, while two cases (100%) of schwannoma also showed 3+ positivity." (PMID 31893185, 2019).
acute lymphoblastic leukemia (3 papers, 2020 to 2022). Leukemia with an acute onset, characterized by the presence of lymphoblasts in the bone marrow and the peripheral blood. "In T-cell acute lymphoblastic leukemia (T-ALL), the expression of TLE1 is significantly decreased, which is associated with disease recurrence and a poor prognosis." (PMID 36438567, 2022). "The aim of this study was to evaluate the prognostic role of TLE1 gene expression in patients with T-cell acute lymphoblastic leukemia (T-ALL)." (PMID 34048198, 2021).
acute myeloid leukemia (3 papers, 2010 to 2016). Acute myeloid leukemia (AML) is a group of neoplasms arising from precursor cells committed to the myeloid cell-line differentiation. "TLE1 is a transducin-like enhancer that is important in hematopoiesis and has been involved with acute myeloid leukemia." (PMID 25663950, 2015). "Both of TLE1 and TLE4 localize in chromosome 9q, the commonly deleted region in acute myeloid leukemia (AML)." (PMID 26701208, 2016).
liver cancer (3 papers, 2017 to 2022). An epithelial or non-epithelial malignant neoplasm that arises from the liver. "A study in Taiwan demonstrated that miRNA-657 bound to the 3′-UTR of TLE1, thereby blocking its inhibitory effect on NF-κB and promoting the invasive ability and spheroid formation capacity of liver cancer cells." (PMID 32432037, 2020). "In liver cancer, the protumorigenic effect of microRNA (miRNA)-657 was found to be related to TLE1 downregulation, suggesting that TLE1 may act as a tumor suppressor in liver cancer." (PMID 36438567, 2022). "Early in 2010, a study showed that in four liver cancer cell lines (HuH6, Hep3B, HepG2, and HLE) down-regulation of TLE1 promoted tumorigenesis, suggesting that TLE1 may act as a tumor suppressor in hepatocellular carcinoma." (PMID 27852056, 2017).
pancreatic cancer (3 papers, 2017 to 2022). "In pancreatic cancer, high levels of TLE1 are associated with a better prognosis, and overexpression of TLE1 inhibits tumor cell proliferation and migration." (PMID 36438567, 2022). "An understanding of the molecular mechanisms underlying TLE1 function is required in order to develop novel targeted therapies for pancreatic cancer and prolong patient survival." (PMID 27852056, 2017). "We focus on the roles of TLE1 in pancreatic cancer and explore targeted approaches for the treatment of this disease." (PMID 27852056, 2017). "In particular, we discuss the TLE1 function in pancreatic cancer." (PMID 27852056, 2017). "However, the mechanisms underlying TLE1 function in pancreatic cancer have not yet been elucidated." (PMID 27852056, 2017). "Thus, additional studies are required to analyze the functions of TLE1 and other TLE family members in pancreatic cancer." (PMID 27852056, 2017). "Additionally, the expression of TLE1 has not been confirmed in pancreatic cancer." (PMID 27852056, 2017).
soft tissue tumors (3 papers, 2019 to 2025). "□ Synovial Sarcoma: Most cases express CD99, BCL-2, and TLE1 proteins, with molecular genetic analysis serving as a critical tool for distinguishing it from other soft tissue tumors." (PMID 40308487, 2025). "We found TLE1 expression in other soft tissue tumors that may enter the differential diagnosis of SS." (PMID 31893185, 2019). "However, the heterogeneity and low specificity of TLE1 expression in non‐SSs should be recognized in the differential diagnosis including epithelioid sarcoma which has shown multifocal positivity in 2 out of 6 cases with 2+ and 3+ staining in a large study of 163 soft tissue tumors." (PMID 35639915, 2022).
type 2 diabetes (3 papers, 2015 to 2022). "Disrupted expression of TLE1 was observed in human type 2 diabetes and is associated with an increased proportion of glucagon-expressing cells." (PMID 36620623, 2022).
carcinosarcoma (2 papers, 2015 to 2025). A malignant tumor composed of a mixture of carcinomatous and sarcomatous elements. "TLE1 may be a useful marker because it is negative in carcinosarcoma, although TLE1 shows limited specificity in the diagnosis of SS as it is expressed in several neoplasms in the differential diagnosis, particularly those of peripheral nerve sheath origin." (PMID 26112006, 2015).
COVID-19 (2 papers, 2021 to 2022). A disease caused by infection with severe acute respiratory syndrome coronavirus 2. "We found the upregulation of TLE1, MAL and ZBTB16 in the tears of COVID-19 patients." (PMID 34615949, 2021).
diffuse large B-cell lymphoma (2 papers, 2017 to 2021). "Interestingly, in hematologic malignancies such as diffuse large B-cell lymphoma and acute myeloid leukemia, reintroduction of TLE1 into hypermethylated leukemia or lymphoma cells resulted in growth inhibition in vitro and in vivo." (PMID 27852056, 2017). "TLE1 in combination with LCP2, TNFRSF9, FUT8, and IRF4 could also be used for molecular subtyping in diffuse large B-cell lymphoma." (PMID 27852056, 2017).
hepatocellular carcinoma (2 papers, 2017 to 2020). A malignant tumor that arises from hepatocytes. "However, in hepatocellular carcinoma, TLE1 can serve as a tumor suppressor." (PMID 32432037, 2020).
Insulin resistance (2 papers, 2022 to 2023). Increased resistance towards insulin, that is, diminished effectiveness of insulin in reducing blood glucose levels.
invasive breast carcinoma (2 papers, 2020 to 2022). A carcinoma that infiltrates the breast parenchyma. "In invasive breast cancer, TLE1 was shown to be significantly associated with the human epidermal growth factor receptor 2+ and triple-negative breast cancer subtypes." (PMID 32432037, 2020). "Analysis of clinical samples demonstrated that TLE1 levels are significantly higher in invasive breast cancer than in noninvasive breast cancer." (PMID 36438567, 2022). "TLE1 is frequently upregulated and may function as an oncogene in certain cancer types, such as NSCLC, invasive breast cancer, and GMB." (PMID 36438567, 2022).
liposarcoma (2 papers, 2017 to 2023). A usually painless malignant tumor that arises from adipose tissue. "Among the patients with liposarcoma, synovial cell or spindle cell sarcoma, the CD45-/VIM+/TLE1+ phenotyping panel identified CTCs in 8/9 patients, ranging from 18 to 3,711 cells, consistent with the prior diagnosis of metastatic disease." (PMID 28403214, 2017).
lymphoma (2 papers, 2021 to 2022). A malignant (clonal) proliferation of B- lymphocytes or T- lymphocytes which involves the lymph nodes, bone marrow and/or extranodal sites. "In addition, overexpression of TLE1 or TLE4 inhibited the in vitro proliferation of lymphoma cells harboring AML1-ETO, and knocking down a TLE homolog promoted the growth of lymphoma in a zebrafish model." (PMID 36438567, 2022).
non-small cell lung carcinoma (2 papers, 2014 to 2016). A group of at least three distinct histological types of lung cancer, including non-small cell squamous cell carcinoma, adenocarcinoma, and large cell carcinoma. "Recently, we showed that the Bit1 pathway is functionally suppressed in Non-Small Cell Lung Carcinoma (NSCLC) as evidenced by the selective downregulation of Bit1 expression and upregulation of the Bit1 inhibitor TLE1 in advanced human lung tumors as compared to normal human lung tissues." (PMID 27655370, 2016).
pancreatic ductal adenocarcinoma (2 papers, 2020 to 2021). An infiltrating adenocarcinoma that arises from the epithelial cells of the pancreas. "However, the mechanisms and prognostic significance of TLE1 in pancreatic ductal adenocarcinoma (PDAC) have not been elucidated." (PMID 32432037, 2020).
prostate carcinoma (2 papers, 2014 to 2022). A carcinoma that arises from epithelial cells of the prostate gland. "RNF6 was reported to promote colorectal cancer by ubiquitination of TLE1 in prostate cancer." (PMID 35568845, 2022).
brain tumour (1 paper, 2018).
childhood asthma (1 paper, 2021). "TLE1 was found to be in the susceptibility locus for childhood asthma as it interacts with RUNX3 to inhibit dendritic cell maturation." (PMID 33791298, 2021).
chordoma (1 paper, 2019). Chordomas are rare malignant tumors arising from embryonic remnants of the notochord in axial skeleton. "TLE1 was negative in all cases of chordomas (n=2), lipomas (n=2), nodular fasciitis (n=2), malignant perivascular epithelioid cell tumor (n=1), and dermatofibrosarcoma protuberans (n=1)." (PMID 31893185, 2019).
esophageal cancer (1 paper, 2023). A primary or metastatic malignant neoplasm involving the esophagus. "constructed a prognostic map for esophageal cancer, utilizing eight genes, including CDCA4, UBE2Z, AMTN, AK1, TLE1, FXN, ZBTB6, and APLN." (PMID 38098487, 2023).
Fibrous Tumour (1 paper, 2020). "However, TLE-1 positivity can also be seen in about 15% of MPNST and about 8% in Solitary Fibrous Tumour." (PMID 32212796, 2020).